MIR642A (microRNA 642a)
Synonyms: hsa-mir-642; MIR642; MIRN642; hsa-mir-642a; mir-642a
Gene: MicroRNA gene on chromosome 19 (45,674,928 to 45,675,024, forward strand). Ensembl gene ENSG00000207773.
Gene Ontology:
Biological process: miRNA-mediated post-transcriptional gene silencing
Cellular component: RISC complex
Homologues: Orthologues: chimpanzee ptr-mir-642 (100% identical), macaque mml-mir-642 (89% identical).